ABCC8 (ATP binding cassette subfamily C member 8)
Diseases named in the same sentence as ABCC8 in open-access papers (continued):
Sharing a sentence is not in itself a finding about the gene and the disease.
Donohue syndrome (2 papers, 2023 to 2024). Leprechaunism is a congenital form of extreme insulin resistance (a group of syndromes that also includes Rabson-Mensenhall syndrome, type A insulin-resistance syndrome, and acquired type B insulin-resistance syndrome) characterized by intrauterine and mainly postnatal severe growth retardation. "Whereas autoimmune monogenic diabetes, Donohue syndrome and Wolcott–Rallison syndrome are known to have a poor prognosis, death in infancy/childhood in patients with PDX1 and ABCC8 pathogenic variants is rare." (PMID 36398453, 2023).
hepatic cancers (2 papers, 2023 to 2025). "This study utilized digital PCR in peripheral blood mononuclear cell (PBMC) samples and reported a potential link between ABCC8 mutations and progression toward liver cancer." (PMID 40981175, 2025).
non-small cell lung carcinoma (2 papers, 2023 to 2025). A group of at least three distinct histological types of lung cancer, including non-small cell squamous cell carcinoma, adenocarcinoma, and large cell carcinoma. "ABCC8 (SUR1) sulfonylurea receptor 1 is a tumor-enhancer in non-small cell lung carcinoma (NSCLC)." (PMID 40149317, 2025).
Sepsis (2 papers, 2023 to 2024). Sepsis is defined as life-threatening organ dysfunction caused by a dysregulated host response to infection. "In summary, deletion of Abcc8 (Abcc8 gene) was associated with an attenuation of axonal swelling, cytotoxic edema, and neuroinflammation in a murine CLP model of sepsis, which was associated with improved cognitive performance." (PMID 36681815, 2023). "Sepsis was induced in 4–6-week-old Abcc8 KO and wild-type (WT) littermate control male mice by CLP." (PMID 36681815, 2023). "We hypothesized that knockout (KO) of Abcc8 is associated with a decrease in microglial activation and brain edema and improved outcomes vs. wild-type (WT) in a murine CLP model of sepsis." (PMID 36681815, 2023). "Using Abcc8 KO mice, we were able to advance the field by defining the contribution of SUR1–TRPM4 to the cytotoxic edema and neuroinflammation that occurs after sepsis." (PMID 36681815, 2023). "Therefore, we hypothesized that knockout (KO) of Abcc8 (Sur1 gene) is associated with a decrease in microglial activation, cerebral edema, and improved neurobehavioral outcomes in a murine cecal ligation and puncture (CLP) model of sepsis." (PMID 36681815, 2023).
status epilepticus (2 papers, 2013 to 2021). Status epilepticus is defined as a continuous seizure lasting more than 30 min, or two or more seizures without full recovery of consciousness between any of them. "In a rat model of status epilepticus, SUR1 and TRPM4 protein and Abcc8/Trpm4 mRNA expression was increased within 6 h and persisted for 3 and 7 days, respectively." (PMID 34769328, 2021).
Abdominal obesity (1 paper, 2022). Excessive fat around the stomach and abdomen. "Thus, the low p-values (<0.05) from association of the ABCC8 gene (rs1799854) with abdominal obesity found among the indigenous people studied here is probably a spurious association and unrelated to biological processes." (PMID 35560161, 2022).
anal carcinoma (1 paper, 2024). "The SMR analyses uncovered the genetic connections of anal carcinoma risk with ABCC8 (OR = 1.762; 95% CI: 1.034–3.022; P-value = 0.037) and DPP4 (OR = 0.100; 95% CI: 0.011–0.893; P-value = 0.039)." (PMID 38504335, 2024). "Strong evidence suggested colocalization between DPP4, GLP1R, ABCC8/KCNJ11, and anal carcinoma." (PMID 38504335, 2024).
atherosclerosis (1 paper, 2022). A disease characterized by the build-up of fatty material and calcium deposition in the arterial wall resulting in partial or complete occlusion of the arterial lumen. "According to our findings, the most significant gene for atherosclerosis was ABCC8, with two relevant variants in the 5′-UTR region (rs2188966 and rs3758953) and a synonymous AGG1273AGA SNP (rs1799859)." (PMID 36314849, 2022).
autism (1 paper, 2013). Persistent deficits in social interaction and communication and interaction as well as a markedly restricted repertoire of activity and interest as well as repetitive patterns of behavior. "Two children with P-CHI, one with a focal lesion due to paternal ABCC8 mutation, and the other with a paternally inherited GCK mutation, developed autism, but did not have MR changes." (PMID 23730298, 2013).
breast tumours (1 paper, 2022). "Nevertheless, the genes ABCA3, ABCA8, ABCA12, ABCC7, and ABCC8 cluster in breast tumours, and the expression of this gene group was associated with the clinical and pathological parameters of tumours." (PMID 35631534, 2022).
cardiac arrest (1 paper, 2021). Cessation of breathing and/or cardiac function. "In a 7 min murine model of asystolic cardiac arrest from KCl injection, Abcc8 and Trpm4 mRNA levels were significantly upregulated at 6 h post-cardiopulmonary resuscitation; Trpm4 levels remained elevated at 24 h." (PMID 34769328, 2021). "After 8 min asphyxial cardiac arrest, both Abcc8 and Trpm4 mRNA, as well as SUR1-TRPM4 protein (western blot), were upregulated in the cortex and hippocampus at 24 h after injury." (PMID 34769328, 2021).
cervical squamous cell carcinoma (1 paper, 2023). A squamous cell carcinoma arising from the cervical epithelium. "This revealed a significant increase in ABCC8 (SUR1) expression in the CIN 3 and cervical squamous cell carcinoma (CSCC) samples." (PMID 37443304, 2023).
cystic fibrosis (1 paper, 2021). Autosomal recessive disorder caused by pathogenic variants in the CFTR gene (cystic fibrosis transmembrane conductance regulator), which encodes a chloride and bicarbonate channel expressed in epithelial cells, and follow the diagnosis criteria. "Multiple intra-intronic and intra-exonic mutations in CFTR (ABCC7), a gene closely related to ABCC8, have been associated with nonfunctional protein and cystic fibrosis disease." (PMID 33529173, 2021).
diabetic retinopathy (1 paper, 2021). "Besides, the frequency of diabetic retinopathy was ~50 percent among the patients with ABCC8 variants." (PMID 34631896, 2021).
Down syndrome (1 paper, 2022). "Genetic testing identified an ABCC8 mutation in one individual with Down syndrome in our cohort and this, together with the finding of an ABCC8 mutation in an individual within the Finnish cohort, highlights the need to perform genetic testing in all individuals with persistent HI." (PMID 35294086, 2022).
duodenal atresia (1 paper, 2022). Duodenal atresia is an embryopathy of the cranial intestine that leads to a complete absence of the duodenal lumen. "Seven individuals, including the child with an ABCC8 mutation, had undergone gastric or oesophageal surgery for duodenal atresia, duodenal stenosis, tracheomalacia, or gastro‐oesophageal reflux disease (GORD)." (PMID 35294086, 2022).
Dyskinesia (1 paper, 2017). A movement disorder which consists of effects including diminished voluntary movements and the presence of involuntary movements. "Among South Asian (SAS) population, Israelis were most abundantly studied representing association of rs393795 (DAT1), rs886292 (ABCC8), rs11880894 (RYR1) and rs1800497 (DRD2) with dyskinesia." (PMID 28927418, 2017).
early-onset epilepsy (1 paper, 2023). "Syndromes characterized by neonatal-onset diabetes and early-onset epilepsy are described (mutations in GCK, INS, KCNJ11, and ABCC8)." (PMID 37048663, 2023).
Eisenmenger syndrome (1 paper, 2022). "Of them, three had at least one P or LP variant: one patient with PAH after the closure of a ventricular septal defect (SOX17), one individual with PAH associated with incidental defects (ABCC8 and SMAD1), and the remaining one with a complex Eisenmenger syndrome (BMPR2)." (PMID 36142358, 2022). "We found a digenic likely pathogenic variant (ABCC8/ SMAD 1) in a case of coincidental PAH and several thoracic collaterals, a pathogenic variant in BMPR2 in a case of PAH after defect closure, and a pathogenic SOX17 variant in a patient with Eisenmenger syndrome." (PMID 36142358, 2022).
glaucoma (1 paper, 2024). Increased pressure in the eyeball due to obstruction of the outflow of aqueous humor. "We further explored genetic associations between ABCC8 and glaucoma‐related endophenotypes, including IOP, RNFL thickness, optic cup area, optic disc area, and vertical cup‐to‐disc ratio using data sets from European ancestry." (PMID 39449751, 2024). "Future studies should investigate the role of ABCC8 and glaucoma endophenotypes in POAG susceptibility." (PMID 39449751, 2024).
hepatic disease (1 paper, 2025). "This supports a multifactorial role for ABCC8 genetic variation in metabolic and hepatic disease, particularly within our South Asian Pakistani cohort." (PMID 40981175, 2025).
hypopituitarism (1 paper, 2023). A condition of diminution or cessation of secretion of one or more hormones from the anterior pituitary gland. "Some of the additional extra‐pancreatic features identified in our cohort were also atypical, for example the presence of hypopituitarism in patient 12 who is compound heterozygous for two ABCC8 variants." (PMID 36398453, 2023).
hypothyroidism (1 paper, 2018). Abnormally low levels of thyroid hormone. "However, hypothyroidism with elevated TSH levels was also reported in two cases with octreotide treated CHI due to ABCC8 gene mutation." (PMID 29217498, 2018).
mucinous ovarian cancer (1 paper, 2026). An invasive malignant neoplasm that arises from the ovary and is characterized by the presence of malignant epithelial cells that contain intracytoplasmic mucin and may resemble the epithelial cells of the endocervix or gastrointestinal tract. "We then performed cis drug-target MR for PPARG, DPP4, ABCC8/KCNJ11, and SLC5A2, integrated triangulation, colocalization, and mediation analyses, and experimentally interrogated the prioritized PPARG/ABCC8-KCNJ11-lactate-invasive mucinous ovarian cancer (IMOC) triangle." (PMID 42278567, 2026).
Neurodevelopmental delay (1 paper, 2020). "One of the patients with neurodevelopmental delay had a paternally inherited ABCC8 mutation and focal CHI, all others had no identified mutation and non-focal CHI." (PMID 32580746, 2020).
oligodendroglioma (1 paper, 2020). A well-differentiated (WHO grade II), diffusely infiltrating neuroglial tumor, typically located in the cerebral hemispheres. "ABCC8 mRNA expression was higher in patients with better prognosis indicators, such as oligodendroglioma, low WHO grade, IDH mutation, 1p/19q col-deletion and low WHO molecular grade (2016)." (PMID 32728190, 2020). "The results showed that ABCC8 mRNA expression was higher in patients with better prognosis indicators, such as oligodendroglioma (p = 1.4e−32), low WHO grade (p = 2.5e−23), IDH mutation (p = 6.4e−20), 1p/19q col-deletion (p = 7.3e−23) and low who molecular grade (2016) (p = 2.8e−35)." (PMID 32728190, 2020). "The patients with oligodendroglioma, low WHO grade, low WHO molecular grade, IDH mutation, and 1p19q deletion had high ABCC8 mRNA expression." (PMID 32728190, 2020).
osteosarcoma (1 paper, 2024). A usually aggressive malignant bone-forming mesenchymal neoplasm, predominantly affecting adolescents and young adults. "Compared to the sham group, the SNL group had higher gene expression levels of Gadd45g (growth arrest and DNA-damage-inducible 45 gamma) and Fos (FBJ osteosarcoma oncogene), while it had lower gene expression levels of Igf1, Ccl2, Hdac2, Rtn4rl1, Nfkb2, Gpr84, Pik3cg, and Abcc8." (PMID 38790607, 2024).
pancreatic adenocarcinoma (1 paper, 2017). "Furthermore, a possible involvement of ABCC8 in pancreatic adenocarcinoma development and progression was recently reported." (PMID 29285254, 2017).
pancreatic ductal adenocarcinoma (1 paper, 2023). An infiltrating adenocarcinoma that arises from the epithelial cells of the pancreas. "We found that the upregulation of the ABCC8 gene was correlated with overall survival in the lung and pancreatic ductal adenocarcinoma with a low risk of progression in white male populations (H.R. values = < 1)." (PMID 37180726, 2023).
paroxysmal tachycardia (1 paper, 2025). A form of tachycardia which begins and ends in an acute (or paroxysmal) manner. "Sulfonylurea targets KCNJ11/ABCC8 were associated with a decreased incidence of paroxysmal tachycardia (OR: 0.69, 95% CI: 0.56, 0.86, PFDR = 0.022)." (PMID 41357784, 2025).
skin cancer (1 paper, 2024). "Insufficient evidence was found for the associations between genetically proxied GLP1R, KCNJ11, ABCC8, and PPARG perturbations and skin cancer risk." (PMID 39640975, 2024).
Supraventricular tachycardia (1 paper, 2025). Supraventricular tachycardia (SVT) is an abnormally increased heart rate (over 100 beats per minute at rest) with origin above the level of the ventricles. "Second, due to the limitations of the original GWAS data, we were unable to further explore the association between KCNJ11/ABCC8 and subtypes of PT (e.g., ventricular tachycardia, supraventricular tachycardia)." (PMID 41357784, 2025).
tumor (17 papers, 2005 to 2026). "Furthermore, TLR signaling within cancer tissues, often initiated by the recognition of tumor-associated antigens or damage-associated molecular patterns (DAMPs) released from stressed or dying cancer cells, is expected to be an additional factor influencing ABCC8 expression." (PMID 38396807, 2024). "The difference in the expression of the five ADME genes (SLC16A1, SLC7A5, SLCO1B1, CYP17A1, and ABCC8) between tumor and normal tissues was significant and was closely correlated with the survival of patients with NSCLC." (PMID 34522968, 2021). "Our study found that the expression of ABCC8 mRNA was negatively correlated with the tumor tissue type, WHO grade, WHO molecular grade, IDH wildtype, and 1p/19q non-codel." (PMID 32728190, 2020). "Our results indicated that the expression of KLKB1 (P < 0.01), IL13RA2 (P < 0.01), ABCC8 (P < 0.01), and PART1 (P < 0.0001) was consistent with our bioinformatics analysis, which was significantly up-regulated in PanNETs compared with the non-tumor tissues." (PMID 31607839, 2019). "The results showed that the expression of KLKB1 (P < 0.01), IL13RA2 (P < 0.01), ABCC8 (P < 0.01), and PART1 (P < 0.0001) was significantly up-regulated, while PCSK2 (P < 0.01) was significantly down-regulated in PanNET tissues compared to the non-tumor tissues." (PMID 31607839, 2019).
cancer (8 papers, 2020 to 2025). A tumor composed of atypical neoplastic, often pleomorphic cells that invade other tissues. "There was little evidence to support associations between genetically proxied PPARG perturbation and colorectal or overall cancer risk or between genetically proxied ABCC8 or GLP1R perturbation with risk across cancer endpoints." (PMID 37171501, 2023). "We found little evidence of association of genetically proxied GLP1R or ABCC8 perturbation with cancer risk." (PMID 37171501, 2023). "There was little MR evidence of association of genetically proxied ABCC8 or GLP1R perturbation with site-specific or overall cancer risk." (PMID 37171501, 2023). "In conclusion, we developed novel instruments for PPARG, ABCC8 and GLP1R using strict validation protocols and evaluated the association of genetically proxied perturbation of these targets with risk of cancer." (PMID 37171501, 2023). "Notably, ABCC8 gene expression exhibits both downregulation and upregulation in cancers such as pancreatic, breast, lung, and colorectal." (PMID 38396807, 2024). "Research focusing on the modulation of ABCC8 expression in cancer cells is currently insufficient." (PMID 38396807, 2024). "This cytokine is speculated to activate the NF-κB pathway, playing a pivotal role in inflammatory responses and the regulation of ABCC8 expression in cancer cells." (PMID 38396807, 2024). "Based on insights from studies in pancreatic beta cells and the CNS, it is hypothesized that ABCC8 expression in cancer cells may be significantly influenced by mechanisms involving hypoxia and inflammation, mediated by TNF-α and TLR signaling." (PMID 38396807, 2024). "KCNJ11, KCNJ8, and ABCC9 genes are upregulated in cancers but ABCC8 is downregulated." (PMID 37180726, 2023). "However, searching for data correlating the gene name and the term cancer yielded data only for the ABCC8 gene." (PMID 37180726, 2023). "This review will further explore the varied expression changes in ABCC8 and ABCC9 in a range of cancers, highlighting their potential impact on cancer behavior and treatment responses." (PMID 38396807, 2024). "Research has demonstrated varying expression patterns of the ABCC8 and ABCC9 genes, crucial in forming KATP channels, across different cancer types." (PMID 38396807, 2024). "This study revealed that the KCNJ8, KCNJ11, ABCC8, ABCC9 genes are downregulated in cancer of the female reproductive tract when compared with the correspondent normal tissues." (PMID 32457608, 2020). "However, expression of the SUR1 (ABCC8) subunit was significantly higher in all four of the HPV+ cancer cell lines examined, with no increase detected in HPV- C33A cells." (PMID 37443304, 2023). "Finally, we found little evidence for an association of genetically proxied ABCC8 and GLP1R perturbation with risk of breast, colorectal, prostate or overall cancer risk." (PMID 37171501, 2023).
retinopathy (2 papers, 2021 to 2024). "The frequency of retinopathy was low, and the presence of microalbuminuria was 0% in ABCC8‐MODY and KCNJ11‐MODY, while microalbuminuria ranged from 1.8% in HNF4A‐MODY and HNF1A‐MODY to 16.7% (1 out of 6 individuals) in KLF11‐MODY." (PMID 39511990, 2024).
ABCC8 also shares sentences with these, for which no sentence is quoted: Hyperinsulinemia (12 papers); Insulin resistance (6); brain injury (5); insulinoma (5); cerebral infarcts (3); COVID-19 (3); genetic disorder (3); Hypertension (3); lung adenocarcinoma (3); maturity-onset diabetes of the young (3); medulloblastoma (3); multiple sclerosis (3); Parkinson disease (3); Arrhythmia (2); Brugada syndrome (2); cardiac hypertrophy (2); colorectal cancer (2); deafness (2); enteropathy (2); glucose metabolism disorder (2); hematoma (2); HIV-1 infection (2); infection (2); neurological diseases (2); Usher syndrome type 1C (2); 5-oxoprolinase deficiency (1); Alzheimer disease (1); angioedema (1); astrocytoma (1); bladder cancers (1).
A further 78 diseases each share a sentence with ABCC8 in 1 paper.